ZNF157 (zinc finger protein 157)
Description:
May be involved in transcriptional regulation.
Synonyms: HZF22
Tractability: PROTAC: ubiquitination databases record sites on it.
Gene: Protein-coding gene on chromosome X (47,370,578 to 47,414,498, forward strand). Ensembl gene ENSG00000147117.
Subcellular location: Nucleus
Subcellular location (Human Protein Atlas): Nucleoplasm; Cytosol
Pathways (Reactome):
Gene expression (Transcription): Generic Transcription Pathway
Gene Ontology:
Biological process: regulation of DNA-templated transcription; regulation of gene expression
Cellular component: nucleus
Homologues: Orthologues: chimpanzee ZNF157 (99% identical), macaque ZNF157 (98% identical), dog ZNF157 (91% identical), guinea pig ZNF157 (88% identical), rabbit ZNF157 (80% identical). Paralogues in human: ZNF33B (53% identical), ZNF182 (52% identical), ZNF717 (52% identical), ZNF658 (51% identical), ZNF41 (50% identical), ZNF33A (50% identical), ZNF484 (49% identical), ZNF334 (49% identical), ZNF605 (49% identical), ZNF250 (48% identical), ZNF300 (48% identical), ZNF546 (48% identical), and 164 more.
Diseases named in the same sentence as ZNF157 in open-access papers:
ZNF157 is named in the same sentence as 9 diseases in open-access papers, as found by Europe PMC text mining. Sharing a sentence is not in itself a finding about the gene and the disease. The quoted sentences say what the papers report.
medulloblastoma (1 paper, 2020). A malignant, invasive embryonal neoplasm arising from the cerebellum. "Notably, ZNF157 was predominantly amplified in the PROM1-centered gene set and this gene has been shown to be epigenetically regulated in medulloblastoma." (PMID 31164716, 2020).
ZNF157 also shares sentences with these, for which no sentence is quoted: chronic fatigue syndrome (1 paper); cutaneous T-cell lymphoma (1); generalized epilepsy (1); male infertility (1); panic disorder (1); personality disorder (1); Pseudoxanthoma elasticum (1); Sezary syndrome (1).